RET (ret proto-oncogene)
Diseases named in the same sentence as RET in open-access papers (continued):
Sharing a sentence is not in itself a finding about the gene and the disease.
tumor (continued). "In alectinib-resistant RET fusion NSCLC cells from another patient, nivolumab or atezolizumab, either alone or in combination with alectinib, did not significant inhibit the growth of tumor cells (102 ± 11%, 75 ± 4%, 74 ± 6%, 79 ± 3%, 75 ± 9% respectively)." (PMID 34488906, 2021). "Thus, in order to conceive more effective and specific treatment, we developed a new gene oriented therapy by siRNA to target RET/PTC3 rearrangement, which is only present in the tumour cells and not in the surrounding normal cells." (PMID 24759995, 2014). "When FRTL (RET/PTC1) cells and FRTL (pcDNA), cells were injected into each of nine nude mice, each mouse developed a single tumor at the site of FRTL (RET/PTC1) cell injection; in contrast, tumor formation never occurred at sites of FRTL (cDNA) cells injection." (PMID 24014739, 2013). "However, 13-cis-RA did not significantly modulate RET, RGS16, FLNB, and EGR1 expression in the tissue samples from tumour-bearing animals treated for 5 days." (PMID 16012519, 2005). "To determine whether RET S649L emerged as a mechanism of targeted or immunotherapy resistance, or as an early event in disease progression, we performed NGS on an FFPE sample of the 2015 treatment-naïve metastasis, as no primary tumor sample was available." (PMID 40756116, 2025). "Out of the 784 samples analyzed by RET-FISH, 24 (3%) were not interpretable, either because of the absence or very poor quality of the hybridization signals (16 samples) or because less than 60 analyzable tumor cells were present on the tissue section analyzed (eight samples)." (PMID 39507413, 2024). "Despite increased MET and RET expression in SCNPC, our results cumulatively suggest that cabozantinib acted through mouse endothelial VEGFR2 and inhibited angiogenesis leading to hypoxia and tumor cell death regardless of MET/RET status in both LuCaP SCNPC PDX models." (PMID 33471819, 2021). "In contrast to results obtained in 3D in vitro assays, RET inhibition and letrozole treatment as monotherapies showed comparable effects in impairing xenograft growth and, moreover, the combination of NVP-AST487 and letrozole had no additional effect on tumor growth." (PMID 27602955, 2016). "They found that low-level RET/PTC recombination occurs in nonneoplastic follicular cells in CLT and in a subset of PTC, suggesting that overlapping molecular mechanisms may govern early stages of tumor development and inflammation in the thyroid." (PMID 25328756, 2014). "Similarly to what observed in TPC-1 and the other RET-activated cell lines in vitro, JAK inhibitor led to a significant decrease of phospho-S6 and phospho-STAT3 levels (p<0.001) in the tumor, while no decrease was observed in vehicle or AZD6244- treated tumors." (PMID 23056499, 2012). "Since, in our study, neither allelic imbalance of RET nor somatic VHL gene alterations occurred in the CCH specimen (presumably the precursor lesion of MTC), we suggest that such somatic VHL gene alterations rather play a role in tumor progression than in tumor formation of MEN2-related MTC." (PMID 16707008, 2006). "Importantly, we found a much higher number of spontaneous metastases with larger tumor volume in the lungs of mice injected with lamin B1–depleted LLC1 cells compared with controls, whereas almost no metastasis was observed in mice injected with RET KD and lamin B1/RET KD LLC1 cells." (PMID 31015297, 2019).
cancer (637 papers, 1996 to 2026). A tumor composed of atypical neoplastic, often pleomorphic cells that invade other tissues. "The RET proto-oncogene encodes a transmembrane receptor tyrosine kinase, and RET mutations drive oncogenic transformation in various cancers." (PMID 40281353, 2025). "Higher response rates were reported in RET fusion-positive cancers (79–89%) than in RET-mutated cases, and they were more effective against RET V804 mutations in MKI-pretreated patients." (PMID 40332222, 2025). "Approximately 70% of PTCs have activation of the MAPK pathway due to BRAF and RAS mutations, as well as RET fusions, which promote cancer progression." (PMID 40911853, 2025). "Targeted therapies, such as selpercatinib and pralsetinib, are used with great success in other types of RET-mutated cancers and hold promise to enhance the CRC treatment options." (PMID 40868288, 2025). "These inhibitors are effective against RET gatekeeper mutations, which are common resistance mechanisms in cancer therapy." (PMID 39925808, 2025). "It will explore actions following identification of a pathogenic germline variant, including predictive, reproductive and childhood testing, and somatic testing of RET variants in solid tumours informing personalised cancer treatment." (PMID 40138217, 2025). "Other pathogenic alterations included p.C620F and p.R912W, both of which have been previously associated with oncogenic signaling in RET-driven cancers." (PMID 40563596, 2025). "Aberrant activation of RET occurs through gene fusions or point mutations, mechanisms that drive oncogenesis in several cancer types." (PMID 41346910, 2025). "RET fusions and point mutations lead to constitutive ligand-independent activation, driving cancer development." (PMID 40576713, 2025). "The activation of RET via gene fusions or point mutations is a potent oncogenic driver in these cancers and in others, such as endometrial and breast cancer." (PMID 41244832, 2025). "A variety of aggressive diseases, such as Hirschsprung disease and cancer, are brought on by mutations that either activate or suppress RET." (PMID 39985107, 2025). "While first-generation inhibitors (selpercatinib, pralsetinib) improve outcomes in RET-altered cancers, solvent-front mutations (notably G810R/S/C) confer therapeutic resistance." (PMID 41181595, 2025). "RET activation in cancer occurs via chromosomal rearrangements and gain-of-function mutations, with elevated wild-type RET expression also contributing to tumourigenesis." (PMID 40141188, 2025). "RET alterations are detected in approximately 2% of human cancers overall, highlighting their importance as diagnostic biomarkers and therapeutic targets." (PMID 41465145, 2025). "New evidence demonstrates an association of altered lncRNA expression to the presence of oncogenic mutations, such as BRAF and RET, in thyroid follicular cell-derived cancers." (PMID 41154428, 2025). "Future research can explore the molecular mechanism of multiple primary cancers (such as the coexistence mode of RET/RAS/BRAF mutation) and evaluate the cost effectiveness of calcitonin screening to optimize clinical practice." (PMID 41261620, 2025). "Selective RET inhibitors (RETis) were developed for RET-altered cancers, including MTC, where RET is the primary driver mutation." (PMID 40332222, 2025). "The transformation of the cancer patient’s condition into a genetic disorder linked to the presence of the RET/PTC kinase is triggered by a series of genomic events." (PMID 40469184, 2025). "Activating mutations of RET or overexpression of the wildtype (WT) protein are established drivers in several cancers." (PMID 38687678, 2024). "Its proper function is crucial for normal cellular signaling and development, and mutations in RET can lead to severe developmental disorders or predispose individuals to cancer." (PMID 39559597, 2024).
cancer (continued). "This is in contrast to driver fusions in other cancers (e.g. EWS-FLI, NRG1, RET), which have often been clearly linked to cancer hallmarks such as activating proliferation, growth factor signaling or invasion/metastasis." (PMID 39149323, 2024). "Considering that RET gene mutations have been detected in most cases of hereditary MTC, these types of MTC, including FMTC and MEN2‐positive cases, can be considered RET gene mutation‐related cancers." (PMID 39410877, 2024). "RET gene alterations, such as fusions or mutations, drive the oncogenic signaling in RET-positive cancers." (PMID 39272672, 2024). "Variant allele frequency (VAF) of RET p.D898_E901del in plasma was 12% (using an MD Anderson cell-free DNA liquid biopsy NGS assay that analyzed 70 cancer-related genes)." (PMID 38438731, 2024). "RET can be expressed and activated in several cancers through point mutations or rearrangements, causing fusion genes." (PMID 39199650, 2024). "Pralsetinib is a selective RET inhibitor approved in 2020 for the treatment of various RET-associated cancers, targeting both wild-type and kinase-activating RET mutations." (PMID 37835559, 2023). "To date, three primary mechanisms of aberrant RET activation have been identified in cancer: in‐frame RET gene fusions, targeted mutations within the RET gene itself, and aberrant overexpression of the RET gene." (PMID 37718634, 2023). "Selpercatinib and pralsetinib are the first generation of specific RET inhibitors used to treat cancers caused by RET mutations." (PMID 37901797, 2023). "This analysis revealed activation of kinases routinely associated with other RTKs (e.g., ALK, EGFR, RET) in cancer." (PMID 37587872, 2023). "Activating RET alterations can occur and lead to uncontrolled cellular proliferation as a hallmark of cancer development." (PMID 37360768, 2023). "Building on previous experience that ICI monotherapy was unsatisfactory, combination therapy has been increasingly applied in RET mutation cancers." (PMID 36865807, 2023). "The cause of the constitutive activation of RET in cancer is due to point mutations in either the extracellular or the kinase domain, or chromosomal rearrangements." (PMID 38001751, 2023). "In this review, we discuss how RET gene changes cause cancer, which cancers have these changes, what tests to use, and how well targeted therapies work." (PMID 37627175, 2023). "The management of TKI-induced and RET inhibitor-associated AEs is of great importance to improve the quality of life and avoid discontinuation, which can lead to a rapid increase in cancer growth." (PMID 36768635, 2023). "Gene mutations that resulted in the oncogenic activation of MAPK signalling pathway have been found to be indispensable in the pathogenesis of many cancers, including RET chromosomal rearrangement, BRAF and RAS point mutations." (PMID 37692064, 2023). "Mutations in the RET gene can result in the activation of the oncogenic potential of the RET protein, thus contributing to the development of cancer." (PMID 37623222, 2023). "Taken together, the results demonstrate that ATOH1 loss promotes cancer stemness through the ATOH1/GAS1/RET/AKT/mTOR signaling pathway in GAC, thus providing a potential therapeutic strategy for AKT/mTOR inhibitors in GAC patients with ATOH1 deficiency." (PMID 37824217, 2023). "RET mutations leading to dysfunctional ligand binding have also been described as the second most significant cancer-predisposing gene in the germline of patients with OS." (PMID 36839989, 2023). "Subsequently, Guisier also determined the effectiveness of ICIs-based combination therapy for RET mutation cancers in a real-world setting." (PMID 36865807, 2023). "Clinical trials are underway to investigate the treatment potential of RET inhibitors in cancers caused by RET mutations." (PMID 38001751, 2023).
cancer (continued). "Herein, we aimed to identify susceptibility genes for familial NMTC and non-RET MTC by whole exome sequencing in 58 individuals belonging to 18 Spanish families with these carcinomas." (PMID 37175550, 2023). "RET fusion-positive carcinomas were associated with high invasiveness and metastatic activity, but probably due to intensive treatment with low patient mortality." (PMID 37882481, 2023). "Aberrant RET signaling in cancers, due to RET mutations, gene fusions, and overexpression, results in the activation of downstream pathways promoting proliferation, differentiation, and survival." (PMID 36254250, 2022). "Rearranged during transfection (RET) is a transmembrane receptor tyrosine kinase that shows targetable mutations and gene fusions in a few types of cancers." (PMID 36358717, 2022). "TAS0953/HM06 also presented effectiveness in pre-clinical analyses, showing cancer cells growth inhibition in cell lines with RET solvent front mutations." (PMID 36358717, 2022). "The proto-oncogene RET encodes a transmembrane tyrosine kinase, and the RET gene mutation is regarded as a significant contributor to the development of numerous cancers, including TC and NSCLC." (PMID 36612173, 2022). "RET gene promotes carcinogenesis primarily by gene fusion, point mutation, and amplification, associated with numerous cancers." (PMID 36582799, 2022). "RET point mutations also exist in a variety of cancers, such as breast cancer (C634R), colorectal adenocarcinoma (V840 M), and gastrointestinal stromal tumor (V840 M)." (PMID 36557971, 2022). "Selpercatinib was also effective and well-tolerated in five pediatric patients with cancers with activating mutations in RET including two patients with MTC." (PMID 34489865, 2021). "These rearrangements that produce chimeric fusion proteins can cause ligand-independent constitutive activation of RET, promoting cancer cell growth, proliferation, and survival." (PMID 33771190, 2021). "Problem 1 asked teams to predict molecules that bound the RETM955T-associated cancer targets RET[M918T], BRAF, SRC, S6K, and avoided binding to MKNK1, TTK, ERK8, PDK1, and PAK3." (PMID 34520464, 2021). "Both gain- and loss-of-function mutations of RET are found in human disease, including cancers with neuroendocrine origin and the intestinal syndrome known as Hirschsprung disease." (PMID 33921066, 2021). "In conclusion, Pz-1 represents a new powerful kinase inhibitor with distinct activity towards cancers induced by oncogenic RET and TRKA variants, including some mutants displaying resistance to other drugs." (PMID 34373541, 2021). "The expression of RET caused significant downregulation in cancer samples compared to the normal control ones (P = 0.002)." (PMID 33906292, 2021). "Nor was there any significant correlation between serum miR-375 levels and age at diagnosis (P = 0.58) or cancer size (P = 0.92), or between serum miR-375 levels and any presence of somatic RET/RAS mutations in MTC tissue (P = 0.35)." (PMID 33854485, 2021). "For instance, in the case of RET, gain-of-function is implicated in several forms of cancer and loss-of-function is linked to developmental disorders and neurodegeneration." (PMID 33857132, 2021). "TT cells are a cancer cell line that originates from the thyroid medulla and harbor a cysteine 634 to tryptophan (C634W) mutation of RET, which is a constitutively activating point mutation." (PMID 33419162, 2021). "There are four key mechanisms for the unusual RET activation in human cancers, including genomic amplification, gain-of-function mutations, chromosomal rearrangements, and autocrine activation." (PMID 33525725, 2021). "Selpercatinib is a targeted, FDA-approved, oral, small-molecule inhibitor for the treatment of rearranged during transfection (RET) proto-oncogene mutation-positive cancer." (PMID 34832869, 2021). "Because V804M-positive RET-altered cancer patients responded to selpercatinib, L730V/I mutations were considered sensitive to selpercatinib." (PMID 34099825, 2021).
cancer (continued). "TPX-0046 is a next-generation RET inhibitor active in drug-resistant cancer models, including solvent front mutations (SFMs) mediated resistance." (PMID 34238332, 2021). "The RET proto-oncogene encodes a transmembrane receptor tyrosine kinase that is involved in oncogenesis in various cancers." (PMID 33419162, 2021). "The U.S. Food and Drug Administration (FDA) has recently approved selpercatinib and pralsetinib, the first targeted therapy for cancer patients with the RET gene mutations." (PMID 34207842, 2021). "Previously reported clinical studies revealed that deregulation or aberrant activation of RET signaling can cause several types of human cancer." (PMID 33525725, 2021). "Altogether, BRAF mutations and RET rearrangements are termed as BRAF-like carcinomas and present similar expression patterns." (PMID 34201607, 2021). "Gain-of-function mutations in RET lead to the development of specific human cancers and have been associated with the regulation of MMPs, including MMP2 and MMP9, which are thought to drive metastasis." (PMID 33020210, 2020). "RET alterations (i.e., RET fusions and point mutations) are implicated in the pathogenesis of lung, thyroid, and other cancers." (PMID 33109256, 2020). "RET fusions allow abnormal expression and activation of the oncogenic kinase, whereas only a few of RET point mutations found in human cancers are known oncogenic drivers." (PMID 35582449, 2020). "The protooncogene RET is a member of the receptor tyrosine kinase family of proteins, and variants of RET have been identified in patients with several types of cancer." (PMID 33178831, 2020). "RET was originally discovered as proto-oncogene, and mutated forms of RET can indeed cause cancer, mainly in the thyroid gland and adrenals." (PMID 32911810, 2020). "Except for MTC and PTC, which have high rates of RET alterations, RET mutations and gene rearrangements have been observed at low frequencies in many types of human cancers." (PMID 35582449, 2020). "Nevertheless, different RET mutations confer different cancer risks, which has led to recommendations for management of the carriers based on the level of risk associated with the specific mutation." (PMID 33167350, 2020). "According to data published in a public database in 2015 (Catalog of Somatic Mutations in Cancer), somatic RET mutations have been detected in 677 of 1662 (41%) samples from patients with MTC." (PMID 33150251, 2020). "Secondary RET mutations that confer the resistance of RET-altered cancers to multikinase inhibitors during therapy have been reported." (PMID 33150251, 2020). "In particular, along with the co-expression of RET with ER-linked genes in BC cell lines and primary cancers, an increased activation of its promoter has been demonstrated with ER stimulation by estrogen." (PMID 35582269, 2019). "While RET-selective agents are improving targeting of RET-associated cancers now, in the future, additional approaches and combinations of therapies will further expand options." (PMID 30666215, 2018). "As part of a positive predictive multigene panel (e.g., ThyroSec v3, or ThyGenX/ThyraMIR), recognition of RET variants can help to distinguish benign lesions from cancer and identify cases requiring surgery." (PMID 30666215, 2018). "The rearranged during transfection (RET) receptor tyrosine kinase is activated in several cancers by somatic mutations or chromosomal rearrangements." (PMID 30038711, 2018). "Although GFL-GFRα complexes have been demonstrated to induce intracellular signaling through other receptors, their role in RET-associated processes is best described in the cancer setting and will be the focus here." (PMID 30666215, 2018). "We performed DNA sequencing of RET exons on matched normal and cancer samples to confirm the presence of the specific mutations identified by NGS." (PMID 29665843, 2018).